CUL3 (cullin 3)
Diseases named in the same sentence as CUL3 in open-access papers (continued):
Sharing a sentence is not in itself a finding about the gene and the disease.
HIV-1 infection (2 papers, 2020 to 2024). The type species of lentivirus and the etiologic agent of acquired immunodeficiency syndrome (AIDS). "Overexpression of Cul3, on the other hand, results in a considerable reduction in HIV-1 infection, demonstrating its potential as a negative regulator of viral replication." (PMID 39600882, 2024). "Since a VSGg-pseudotyped virus takes an entirely different route of entry into cells compared to wild type HIV-1, we went on to explore the effect of Cul3 on HIV-1 infection in the context of the natural entry route." (PMID 32882949, 2020). "To validate the effect of Cul3 on HIV-1 infection using an orthogonal approach, we overexpressed increasing amounts of Cul3 cDNA in HEK293T cells and infected the cells using a VSVg-pseudotyped HIV-1 NL4-3 reporter virus." (PMID 32882949, 2020). "To establish if Cul3 is expressed in the cell types that are relevant in the context of HIV-1 infection, we analyzed protein expression by western blot in an immortalized T cell line (Jurkat cells) and an immortalized monocytic cell line (THP-1 cells)." (PMID 32882949, 2020). "Our data indicate that the inhibitory effect of Cul3 on HIV-1 infection relies on the region in the viral LTR that harbors the NF-κB binding sites." (PMID 32882949, 2020). "After we verified that Cul3 is expressed in cells of the human immune system that are relevant for HIV-1 infection, we next sought to investigate the effect of Cul3 on HIV-1 replication in infected primary CD4+ T cells." (PMID 32882949, 2020). "Transfecting HEK293T cells with increasing amounts of Cul3 cDNA resulted in elevated Cul3 protein levels and decreased HIV-1 infection in a dose-dependent manner up to 75%." (PMID 32882949, 2020). "In the present study, we investigate the role of the E3 ubiquitin-protein ligase Cul3 in the context of HIV-1 infection." (PMID 32882949, 2020). "Analysis by qRT-PCR in the context of wild type HIV-1 infection revealed an 8-fold increase of viral mRNA expression after Cul3 knock down compared to cells treated with control siRNA." (PMID 32882949, 2020). "Conversely, overexpression of Cul3 reduces HIV-1 infection in single replication cycle assays." (PMID 32882949, 2020). "Interestingly, overexpression of Cul3 in HEK293T cells reduced HIV-1 infection." (PMID 32882949, 2020). "In the present study, we show that Cul3 is expressed in HIV-1 target cells, such as CD4+ T cells, monocytes, and macrophages and depletion of Cul3 using siRNA or CRISPR/Cas9 increases HIV-1 infection in immortalized cells and primary CD4+ T cells." (PMID 32882949, 2020). "Importantly, Cul3 was detected in activated CD4+ T cells, the primary target of the virus, which further supports a role of this factor in regulating HIV-1 infection." (PMID 32882949, 2020).
Insulin resistance (2 papers, 2023 to 2024). Increased resistance towards insulin, that is, diminished effectiveness of insulin in reducing blood glucose levels. "While the KLHL9/KLHL13/CUL3 complex has been primarily implicated in regulating cell cycles, insulin resistance and cancer, its role in infectious diseases has remained largely unexplored." (PMID 38834545, 2024).
Noonan syndrome (2 papers, 2020 to 2022). Noonan Syndrome (NS) is characterized by short stature, typical facial dysmorphism and congenital heart defects. "For instance, CUL3 and LZTR1, an adaptor for the CUL3 Ub ligase complex, have been linked to familial hypertension and Noonan syndrome, respectively, both of which exhibit cardiac defects." (PMID 33391028, 2020). "LZTR1 functions as a component of the CUL3 E3-ligase complex, which mediates the degradation of RAS and is a tumor suppressor gene that can cause schwannomatosis and Noonan syndrome." (PMID 35706047, 2022).
ovarian tumors (2 papers, 2014 to 2021). "Similarly, the CULLIN 3 (CUL3) E3 ligase complex promotes K48-linked polyubiquitination of BECLIN1 and is associated with reduced autophagy, promoting the proliferation of breast and ovarian tumour cells." (PMID 34204202, 2021).
periodontitis (2 papers, 2021 to 2025). An acute or chronic inflammatory process that affects the tissues that surround and support the teeth. "Regarding the detrimental effect of CUL3 in exacerbating periodontitis, the application of DI‐1548 and DI‐1859, potent and selective inhibitors of CUL3, offer promising therapeutic strategies for treating periodontitis." (PMID 39626954, 2025). "Given the essential regulatory role of CUL3 in periodontitis, CUL3 may represent a potential therapeutic target for periodontitis." (PMID 39626954, 2025). "CUL3 in periodontitis promotes cell inflammation and apoptosis." (PMID 34193016, 2021). "CUL3 degrades Keap1 and then activates Nrf2 in periodontitis." (PMID 34193016, 2021). "CUL3 degrades Gli1 and then down-regulates Nrf2 in periodontitis." (PMID 34193016, 2021). "E3s, including Cullin3 (CUL3), Nedd4‐2, Synoviolin, FBXL19, PDLIM2, TRIMs and TRAFs have been identified as key players in modulating periodontitis." (PMID 39626954, 2025). "Increasing evidence indicated that E3s, such as CUL3, Nedd4‐2, Synoviolin, FBXL19, PDLIM2, TRIMs and TRAFs, modulate inflammatory responses and bone resorption in periodontitis through multiple classical signalling pathways, including NLRP3, GSDMD, NF‐κB, Wnt/β‐catenin and Nrf2." (PMID 39626954, 2025). "However, the regulatory role of CUL3,SHH/Gli, and NRF2 in periodontitis has not been reported so far." (PMID 34193016, 2021).
pseudohypoaldosteronism (2 papers, 2023). An inherited or acquired disorder of electrolyte metabolism, characterized by the inability of the renal tubules to respond to aldosterone. "Nine patients were confirmed with aldosterone resistance, of which one child was diagnosed with pseudohypoaldosteronism (PHA) type 1 with a mutation in the NR3C2 gene and 3 children were identified with PHA type 2 due to novel mutations in either the CUL3 or KLHL3 genes." (PMID 36726778, 2023).
Stroke (2 papers, 2015 to 2021). Sudden impairment of blood flow to a part of the brain due to occlusion or rupture of an artery to the brain. "In the future, significant proteins including UBC, CUL3, APP, NEDD8, JUP, SIRT7, etc., can be potent drug targets for first aid and emergency treatment within 24 h post-stroke." (PMID 26679092, 2015).
adenovirus infection (1 paper, 2013). "The presented data also indicate the involvement of the functional Cul3 protein during productive adenovirus infection." (PMID 24260437, 2013). "Based on our presented results it became of interests to evaluate the role of the Cul3 protein during the adenovirus infection." (PMID 24260437, 2013).
age-related macular degeneration (1 paper, 2020). Age-related loss of vision in the central portion of the retina (macula), secondary to retinal degeneration. "The study of the effects of miR-601 expression on CUL3 and NRF2 signaling revealed that this miRNA could participate in a dependent CUL3-KEAP1-NRF2 activation mechanism, thus suggesting a possible therapeutic strategy for treatment or prevention of Age-related macular degeneration (AMD)." (PMID 33287295, 2020).
AIDS (1 paper, 2020). A syndrome resulting from the acquired deficiency of cellular immunity caused by the human immunodeficiency virus (HIV). "Understanding how Cul3 restricts HIV-1 transcription could potentially lead the way towards new approaches for HIV/AIDS therapies and may provide novel strategies to clear the HIV-1 reservoir from infected individuals." (PMID 32882949, 2020).
asthenozoospermia (1 paper, 2022). "The mRNA expression of COPS7A was upregulated in patients with asthenozoospermia, but the expression of CUL3, KLHL7, and NEDD4 was downregulated in these patients." (PMID 36471356, 2022). "Finally, we found that the COPS7A was significantly upregulated in patients with asthenozoospermia, but CUL3, KLHL7 and NEDD4 were significantly downregulated compared with normal samples." (PMID 36471356, 2022). "A western blotting assay using 16 semen samples (including 8 asthenospermia and 8 normal samples) revealed similar results, indicating COPS7A was significantly upregulated in patients with asthenozoospermia, but CUL3, KLHL7 and NEDD4 were significantly downregulated compared with normal samples." (PMID 36471356, 2022). "The intersection among two groups of hub genes included COPS7A, CUL3, KLHL7, and NEDD4, which can be considered the main key genes in asthenozoospermia." (PMID 36471356, 2022). "A Venn analysis was used to identify four key genes based on two methods, including COPS7A, CUL3, KLHL7, NEDD4, which may be potentially important genes in asthenozoospermia." (PMID 36471356, 2022).
astrocytoma (1 paper, 2017). "PTPN6 and CUL3 were the key hub genes identified in the astrocytoma relative to the oligodendroglioma." (PMID 28924174, 2017).
Atrophy (1 paper, 2015). Any weakening or degeneration, especially through lack of use. "Therefore, despite the fact that at 24 wks of age AR113Q male mice already show symptoms of the disease accompanied by signs of muscle atrophy and MyoG activation, the catabolic activity of muscle proteins mediated by atrogin-1, MuRF-1 and Cullin-3 ubiquitin ligases did not take place yet." (PMID 26490709, 2015).
bladder tumours (1 paper, 2013). "Our findings were innovative and clinically relevant since Cul3 expression was linked to the invasive/metastatic phenotype in human bladder tumors, and also revealed that this protein can be secreted to the extracellular matrix." (PMID 23308193, 2013). "Significant statistical associations were found between Cul3 nuclear over-expression and increasing tumor stage when comparing non-invasive versus muscle-invasive bladder tumors (p = 0.001, n = 284)." (PMID 23308193, 2013). "Cul3 immunohistochemical protein patterns performed on bladder tumours spotted onto tissue microarrays (n = 284), were associated with tumor staging, lymph node metastasis and disease-specific survival." (PMID 23308193, 2013). "Overall, expression patterns of Cul3 in bladder tumors suggested its role as a biomarker for tumor stratification, metastasis and clinical outcome prognosis." (PMID 23308193, 2013). "Differential expression was observed for Cul3 among the bladder tumors tested." (PMID 23308193, 2013). "Primary invasive bladder tumors that developed lymph node metastases showed higher expression levels of Cul3 as compared to those with negative lymph nodes (p = 0.025)." (PMID 23308193, 2013).
breast tumors (1 paper, 2016). "Cullin 3 (Cul3) gene expressions was also studied in breast tumors from Maitake‐treated and ‐untreated mice." (PMID 27401257, 2016).
Cerebral ischemia (1 paper, 2025). Restriction of arterial blood supply to the brain associated with insufficient oxygenation to support the metabolic requirements of the tissue. "Among the identified genes, CUL3 may exacerbate neuronal apoptosis and aggravated cerebral ischemia–reperfusion injury by negatively regulating the Nrf2 signaling pathway." (PMID 40299522, 2025).
cholangiocarcinoma (1 paper, 2023). A carcinoma that arises from the intrahepatic biliary tree (intrahepatic cholangiocarcinoma) or from the junction, or adjacent to the junction, of the right and left hepatic ducts (hilar cholangiocarcinoma). "For instance, one study reported that CUL3 deficiency altered the tumor microenvironment and induced cholangiocarcinoma development." (PMID 37999208, 2023).
chronic obstructive pulmonary disease (1 paper, 2021). A chronic and progressive lung disorder characterized by the loss of elasticity of the bronchial tree and the air sacs, destruction of the air sacs wall, thickening of the bronchial wall, and mucous accumulation in the bronchial tree. "Evidence has shown their capability to increase the expression of NRF2 target genes in cellular and in vivo models of chronic obstructive pulmonary disease (COPD), and to interfere with the direct PPI between KEAP1 and NRF2 or the PPI between KEAP1 and CUL3." (PMID 34663413, 2021).
congenital myopathy (1 paper, 2023). "In particular, KLHL40 and KLHL41, that functions as substrate-specific adaptors for E3 ubiquitin ligase CUL3, contribute to severe forms of congenital myopathy with neonatal lethality with extensive sarcomeric disarray and contractures." (PMID 37432316, 2023).
diabetic retinopathy (1 paper, 2025). "Indeed, it was recently shown that NRF2 expression and activity is reduced in the streptozotocin-induced rat model of diabetic retinopathy and that inhibition of NRF2 degradation by an inhibitor of Cullin-3 neddylation alleviates DR by counteracting oxidative stress and inflammation." (PMID 41205411, 2025).
Ewing sarcoma (1 paper, 2021). A small round cell tumor that lacks morphologic, immunohistochemical, and electron microscopic evidence of neuroectodermal differentiation. "Together, these data further support a physiological role of SPOPCUL3 in targeting EWS–FLI1 for degradation and suggest that Ewing sarcoma tumors may inactivate SPOP‐mediated EWS–FLI1 degradation through CUL3 mutations to promote Ewing sarcoma growth." (PMID 34060252, 2021). "Exploring genetic alterations in Ewing sarcoma cells (DEPMAP portal), we noted a point mutation in CUL3 (E358Q) that was present only in EWS502 cells." (PMID 34060252, 2021).
glioma (1 paper, 2020). A benign or malignant brain and spinal cord tumor that arises from glial cells (astrocytes, oligodendrocytes, ependymal cells). "Klhl21 is known to bind E3 ubiquitin ligase through Cul3 and Klhl30 has been identified as a circadian pathway gene involved in the onset of glioma." (PMID 33043001, 2020).
Hyperchloremia (1 paper, 2024). An abnormally increased chloride concentration in the blood. "Functional enrichment analysis revealed that oral poisoning owing hyperchloremia is associated with 4 proteins e.g. Kelch-like protein 3, Serine/threonine-protein kinase WNK4, Serine/threonine-protein kinase WNK1 and Cullin-3." (PMID 38615119, 2024). "Through a comprehensive genome-wide analysis concentrating on genes related to oral poisoning and hyperchloremia, we investigated the metabolic pathway involving proteins like Cullin-3." (PMID 38615119, 2024).
Hypercholesterolemia (1 paper, 2013). An increased concentration of cholesterol in the blood. "Among the DEGs that were down-regulated in the hypercholesterolemia plus sham group vs. sham controls were beta tropomyosin (LOC100125984), PFDN5 and CUL3." (PMID 23874591, 2013).
Hyperglycemia (1 paper, 2024). An increased concentration of glucose in the blood. "Similarly, treating MLN4924 chronically to western diet (WD)-fed mice rescues hyperglycemia through inhibiting CUL3 neddylation." (PMID 38212312, 2024). "In contrast to the results from CUL1 knockdown, knockdown of CUL3 or CUL5 did not improve the hyperglycemia of HSD flies." (PMID 38212312, 2024).
insomnia (1 paper, 2017). A sleep disorder characterized by difficulty in falling asleep and/or remaining asleep. "Since insomnia tends to become more prevalent with age in humans, we asked whether expressing faf in clock cells would disrupt sleep from the first day of life, similar to the results seen with inc and Cul-3, or whether the changes in sleep would develop over time in adults." (PMID 29109678, 2017).
lymph node metastasis (1 paper, 2013). "A high intensity and the presence of Cul3 in the extracellular matrix were also associated with increasing stage (p = 0.004, and p = 0.005, respectively), and with the presence of lymph node metastasis (p = 0.002, and p = 0.001)." (PMID 23308193, 2013).
Macrocephaly (1 paper, 2024). Occipitofrontal (head) circumference greater than 97th centile compared to appropriate, age matched, sex-matched normal standards. "From these genes, four are associated either with microcephaly (CUL3 [MIM: 603136]) or macrocephaly (CDH2 [MIM: 114020], GLI3 [MIM: 165240], and WNT5A [MIM: 164975])." (PMID 39168120, 2024).
morphine dependence (1 paper, 2024). Strong dependence, both physiological and emotional, upon morphine. "Taken together, the results demonstrated that CUL3/KCTD5 regulates morphine dependence via modulating the sensitization of AC in PVT." (PMID 39008526, 2024). "Another important finding of the present study is to uncover the roles of CUL3/KCTD5-mediated AC1 sensitization in morphine dependence." (PMID 39008526, 2024).
muscle atrophy (1 paper, 2022). The loss of muscle tissue due to inactivity or disease. "In conclusion, we identified that CUL3 and COPS5 may be novel prognostic biomarkers in muscle atrophy based on bioinformatics analysis." (PMID 35815279, 2022). "Furthermore, CUL3 and COPS5 are related to the ubiquitin-proteasome pathway, which may provide useful ideas for the study of the pathogenesis of muscle atrophy." (PMID 35815279, 2022).
neuroblastoma (1 paper, 2022). Neuroblastoma (NB) is the most common solid, extracranial childhood tumor. "Treatment of M17 neuroblastoma cells (concentrations up to 10 μM) with CuL1, CuL3 and CuL4 did not significantly impact cell health as measured by both assays." (PMID 36142627, 2022).
osteonecrosis (1 paper, 2017). A none disease characterized by death of bone tissue due to a lack of blood supply. "Expressions of miR-455 and Cul3 in human osteoporosis and osteonecrosis tissues should also be tested in future studies." (PMID 28938631, 2017).
Parkinson disease (1 paper, 2022). A progressive degenerative disorder of the central nervous system characterized by loss of dopamine producing neurons in the substantia nigra and the presence of Lewy bodies in the substantia nigra and locus coeruleus. "GSEA results showed that CUL3 was related to Parkinson's disease, ECM-receptor interaction, and oxidative phosphorylation." (PMID 35815279, 2022).
preeclampsia (1 paper, 2022). Preeclampsia is a hypertensive disorder of pregnancy that is characterized by new-onset hypertension with proteinuria presenting after 20 weeks of gestation, and depending on mild or severe forms may initially present with severe headache, visual disturbances, and hyperreflexia. "However, prior works have also described altered levels of Keap1 and CUL3 in other pregnancy complications, such as preeclampsia, suggesting its potential role in the pathophysiology of obstetric diseases." (PMID 36421463, 2022).
promyelocytic leukemia (1 paper, 2022). "Zinc finger and BTB domain containing 16 (ZBTB16), also named as Zfp145 or promyelocytic leukemia zinc finger, can mediate the binding of Cullin 3 (CUL3) to form CUL3-ZBTB16 complexes." (PMID 35109896, 2022).
Pseudohypoaldosteronism type IIE (1 paper, 2015). "Pseudohypoaldosteronism type IIE (PHA2E) is caused by heterozygous mutation in the CUL3 gene on chromosome 2q36." (PMID 26294796, 2015).
Restless Leg Syndrome (1 paper, 2012). "Interestingly, Cul3 has also been linked to sleep behavior via a candidate gene for Restless Leg Syndrome (RLS) and BTB gene, BTBD9." (PMID 23055946, 2012).
sarcopenia (1 paper, 2022). Progressive decline in muscle mass due to aging which results in decreased functional capacity of muscles. "Additional studies have used gene expression and structural analysis to identify CUL3 associated with sarcopenia." (PMID 35815279, 2022).
schwannoma (1 paper, 2022). A benign, usually encapsulated slow growing tumor composed of Schwann cells. "We were struck by this result since LZTR1, a member of the Kelch-like (KLHL) family and an adapter for Cullin 3 (CUL3) ubiquitin ligase complexes, is considered a tumor suppressor in schwannoma and glioblastoma." (PMID 35197475, 2022).
Seizure (1 paper, 2024). A seizure is an intermittent abnormality of nervous system physiology characterized by a transient occurrence of signs and/or symptoms due to abnormal excessive or synchronous neuronal activity in the brain. "In addition, patients with CUL3 pathogenic variants may have seizures, congenital heart defects, dysmorphic facial features, and abnormal brain imaging." (PMID 40225944, 2024).